INS (insulin)
Diseases named in the same sentence as INS in open-access papers (continued):
Sharing a sentence is not in itself a finding about the gene and the disease.
Hyperglycemia (continued). "They exhibited notable hyperglycemia and significant impairment in glucose handling when compared to the controls, as revealed by glucose tolerance test (GTT) and insulin tolerance test (ITT)." (PMID 36711657, 2023). "Interestingly, even when compared to 46, XX women with primary ovarian insufficiency, women with TS demonstrate significant impairments in oral glucose-stimulated insulin secretion, which implicates Xchr factors, independent of estrogen deficiency, in the TS hyperglycemia phenotype." (PMID 36875465, 2023). "While these have only shown small overall benefits over standard insulin analogues when applied in HCL systems, there is evidence of reduced postprandial hyperglycaemia, particularly after a missed meal bolus." (PMID 37289734, 2023). "By alleviating insulin release and IR, EPE effectively ameliorated hyperglycemia possibly by modulating enzymes involved in glycogenesis and gluconeogenesis." (PMID 37397470, 2023). "Although both treatments ameliorate hyperglycemia and NASH, insulin treatment alone lead to suppression of HCC accompanied by improvement of dysbiosis and restoration of antimicrobial peptide production." (PMID 37852976, 2023). "The differences in treatment modalities, with more women with T2D requiring both metformin and insulin in the third trimester, and at higher doses, than women with GDM, also suggests greater severity of hyperglycemia." (PMID 37608089, 2023). "Clinical outcomes included mean blood glucose (MBG), hypoglycemia, hospital length of stay, hyperglycemia, surgical site infection (SSI) and mean total daily insulin." (PMID 37674887, 2023). "On the other hand, it is known that both intestinal insulin/IGF1 signaling through FoxO1 and hyperglycemia regulate epithelial integrity and drive intestinal barrier dysfunction." (PMID 36986052, 2023). "Although the exact mechanism by which β-cell-specific GLS2 regulates insulin and glucagon requires further study, our data indicate that GLS2 in pancreatic β-cells maintains glucose homeostasis under the condition of hyperglycaemia." (PMID 37147373, 2023). "In this study, FMT significantly improved hyperglycemia symptoms in T2DM mice, including decreased water intake, reduced blood glucose and insulin levels, and alleviated urinary output." (PMID 37894615, 2023). "Automated insulin delivery systems have been found to not only improve HbA1c, but also to improve the percentage of time glucose is in the target range and may reduce events of hyperglycemia and hypoglycemia when compared with sensor-augmented insulin pump therapy." (PMID 37176759, 2023). "They exhibited notable hyperglycemia and significant impairment in glucose handling when compared to the controls, as revealed by the glucose tolerance test (GTT) and insulin tolerance test (ITT)." (PMID 37144869, 2023). "Even though exogenous insulin is used to treat T1DM, patients can become insulin-dependent, leading to attacks of hypoglycemia or hyperglycemia and poor quality of life." (PMID 38813509, 2023). "Despite GIP’s suggested role in insulin sensitivity in healthy individuals, GIP resistance has been observed in a T2D state when hyperglycaemia reduces GIP receptor expression in β-cells." (PMID 38049854, 2023). "Further, a case of a man with pasireotide-induced hyperglycaemia successfully treated with a combination of GLP1-RA, insulin and empaglifozin was also reported." (PMID 37842314, 2023). "Also, if insulin and food intake are not correctly adjusted to physical activity, exercise may contribute to increased risk of both hypoglycemia and hyperglycemia." (PMID 36964201, 2023). "Unexpectedly, women with postload hyperglycemia (raised glucose at 1-hour and/or 2-hour timepoints during the OGTT) had comparable insulin indices as the euglycemic women in the cohort." (PMID 36950879, 2023).
Hyperglycemia (continued). "Dulaglutide is a highly efficacious treatment for hyperglycemia in T2D that was developed based on incretin physiology, as GLP-1 is released after nutrient ingestion and stimulates glucose-dependent secretion of insulin." (PMID 36894938, 2023). "AGE-induced free radical production and elevated oxidative stress-induced reduction in insulin secretion and GLUT4 translocation could cause a futile cycle because it involves the continuous accumulation of glucose in the blood, which is also known as hyperglycemia." (PMID 37894687, 2023). "In pasireotide-related hyperglycaemia the combination of metformin and GLP1-RA is strongly recommended, and in cases of poor glycaemic control insulin treatment should be used." (PMID 37842314, 2023). "Relative to UCB-MSCs and BM-MSCs, WJ-MSCs demonstrated a superior potential to differentiate into glucose stimulated insulin secreting (GSIS) cells and for better hyperglycemia control in type 1 diabetes (T1D) animal models." (PMID 37440921, 2023). "Chronic hyperglycemia increases CREB ubiquitination and decreases protein expression which ultimately inhibits insulin secretion." (PMID 37601108, 2023). "Hyperglycaemia is considered an on-target effect of PI3K inhibitors, which is relevant to the crucial role of the PI3K pathway in insulin signalling and glucose homeostasis." (PMID 36773078, 2023). "Multiple reports have demonstrated that human pseudoislets contain more insulin, perform better than native islets in glucose-stimulated insulin secretion (GSIS) in vitro and improve hyperglycemia in vivo when transplanted in mice." (PMID 37760571, 2023). "The duration to reverse hyperglycemia varied disproportionately with RBS and ranged from 12 to 72 hours (iv followed by s/c insulin)." (PMID 37719546, 2023). "AFA also reduced hyperglycaemia, insulinaemia, HOMA-IR and ameliorated the glucose tolerance and the insulin response of obese mice." (PMID 38067134, 2023). "It is still uncertain whether stress‐induced hyperglycemia has direct effects on adverse outcomes in ACS patients, as there is little evidence from clinical trials supporting the survival benefits associated with intensive insulin treatment in patients after ACS." (PMID 37132473, 2023). "Hyperglycemia-induced AGE production and binding to their receptor RAGE impair insulin signal transduction by triggering a number of signaling pathways, including JNK, NF-κB, and PKC activation." (PMID 37886939, 2023). "Treatment with troglitazone prevented hyperglycemia and the adverse effects on PDX-1 and insulin gene expression and improved insulin secretion." (PMID 36834496, 2023). "A study of GLU, TG, and INS in peripheral serum found that SAMP8 mice had obvious metabolic disorders, manifested as hyperglycemia, hyperlipidemia, and hyperinsulinemia." (PMID 38283741, 2023). "The combination of basal insulin and GLP‐1RA can thus resolve the two issues of hyperglycemia in T2DM patients." (PMID 37864379, 2023). "IGT, on the other hand, shows more severe β-cell dysfunction with significantly reduced glucose-induced insulin secretion in both early and late stages, results in post-OGTT hyperglycemia." (PMID 37402708, 2023). "A high baseline insulin level in T2DM will start a vicious cycle of hyperlipidemia and hyperglycemia." (PMID 36819346, 2023). "For cells relying on insulin-independent GLUT transporters (e.g., GLUT1) intracellular glucose concentration will increase in response to hyperglycemia, thereby promoting AGE-modification of cytosolic proteins." (PMID 37371869, 2023). "Not only does hyperglycemia cause vascular dysfunction, but vascular lesions also precede and contribute to hyperglycemia in T2DM by impairing insulin-mediated glucose handling and possibly insulin secretion." (PMID 37444337, 2023). "Excess cholesterol in pancreatic β-cells undermines glucose-stimulated insulin secretion by disturbing the function of organelles, GLUT-2 and K+ -ATP channels, resulting in hyperglycemia." (PMID 35571202, 2022).
Hyperglycemia (continued). "Pretreated with insulin, the 1BR.3.N WWOX OE fibroblasts, showed a significant (p < 0.05) increase in glucose uptake in the normoxia hyperglycemia, but glucose uptake decrease in hypoxia normoglycemia and hyperglycemia in comparison to 1BR.3.N WT." (PMID 35328751, 2022). "Several studies have demonstrated that during chronic hyperglycemia, oxidative stress is induced in β-cells and compromises the expression of MAFA, which leads to reduced biosynthesis and secretion of insulin." (PMID 35562869, 2022). "However, other studies indicate that the protective effect of hyperglycemia in preventing the aortic aneurysm development process could be diminished by insulin treatment and that DM results in impaired activation of the protective anti-inflammatory pathway in vascular inflammation." (PMID 36330007, 2022). "Three significant flaws characterize the start of hyperglycemia in T2DM: Hepatic glucose synthesis increases, insulin secretion decreases, and insulin action is hampered." (PMID 36060389, 2022). "This study provides important longitudinal data linking the development of hyperglycemia through CRP and insulin salivary inflammatory biomarkers." (PMID 35757631, 2022). "Hyperglycemia results in islet capillary dilation and redistribution of IBF leading to increased insulin release through central parasympathetic signalling." (PMID 36327900, 2022). "Glucose and insulin impact on the BMI-1 dependent regulation of PHLPP-analyzed cells with the downregulation of BMI-1 expression in hypo-, normo-, and hyperglycemia conditions and stimulation by insulin." (PMID 36497428, 2022). "Co-culture with mannoheptulose had little effect on glucose-stimulated insulin secretion (GSIS) or insulin content in LG-cells, but largely prevented the dramatic reduction in GSIS and insulin content produced by chronic hyperglycaemia." (PMID 36376280, 2022). "In the animal experiment on DM II, ACP can significantly improve the hyperglycemia symptoms of DM II mice, reduce blood lipid, reduce liver and kidney injury, and increase the contents of SOD, liver glycogen, and insulin." (PMID 35627036, 2022). "Mice with liver-specific double IRS1 and IRS2 knockout exhibit severe hyperglycemia, suggesting that hepatic IRS1 and IRS2 are the critical mediators of insulin’s regulation of glucose metabolism." (PMID 35074429, 2022). "To exclude the interference of hyperglycemia, we performed an EHC study, the gold standard for evaluating insulin sensitivity, and measured circulating GPHB5 levels in women with IR and PCOS and normal individuals." (PMID 36568071, 2022). "Depletion of CREB activity in pancreatic β-cells leads to hyperglycemia due in part to diminished expression of IRS-2, excessive β-cell apoptosis and decreases in insulin secretion." (PMID 35308228, 2022). "GLP-1 physiologically induces glucose-dependent insulin secretion from β-cells and GLP-1 analogues improve hyperglycemia in T2D patients." (PMID 36557308, 2022). "Moreover, leptin administration has achieved promising results in insulin-deficient rodent models, which indicated leptin could reverse hyperglycemia independent of insulin." (PMID 34996484, 2022). "In addition, giving that insulin is mainly metabolized by the liver, the scavenging effect of liver on insulin decreases under pathological conditions, and clinically presenting with hyperinsulinemia, characterized by frequent fasting hypoglycemia and postprandial hyperglycemia." (PMID 35692404, 2022). "While GIP loses its insulinotropic effect in T2D with chronic hyperglycemia, GLP-1 is still able to stimulate insulin secretion." (PMID 36313764, 2022). "Nanoparticles of selenium have received great attention for their unique biological activities and low toxicity and can alleviate hyperlipidemia, hyperglycemia, and in STZ-induced diabetic rats, possibly by eliciting insulin-mimetic activity." (PMID 36080407, 2022).
Hyperglycemia (continued). "For hypo- and hyperglycemia prevention during and after physical activity, the DDG gives strategies for adjusting the amount of insulin or the intake of additional carbohydrates." (PMID 36231598, 2022). "The elevated insulin levels seen in T2DM and IR augment the expression of SGLT2 and so worsen not only hyperglycaemia but also sodium and fluid retention." (PMID 35529461, 2022). "Furthermore, insulin use was associated with better mortality outcomes on time-dependent 42-day survival analysis compared to both patients without DM/hyperglycemia (p = 0.04) and those with DM/hyperglycemia not receiving insulin (p = 0.03)." (PMID 36675866, 2022). "In preterm babies with hyperglycemia on the NICU, should intravenous administration of insulin be proceeded by priming of the intravenous system, adding of albumin, or non-priming to get a stable insulin dose?" (PMID 36542240, 2022). "After hyperglycemia had persisted for 4 weeks, we treated STZ-induced diabetic WT mice and NOD mice with insulin or an CX3CL1 neutralizing antibody for 2 weeks." (PMID 35370759, 2022). "SZ-A, the extract of Morus alba L., has been shown to reduce hyperglycemia in patients and was approved for T2DM treatment in 2020, including the regulation of α-glucosidases, insulin sensitivity, microbiota, and inflammation." (PMID 35624769, 2022). "As explained later, activation of PKB inactivates FOXO and stimulates insulin gene expression, but in chronic hyperglycemia and oxidative stress, this pathway is weakened in β-cells and PDX1 and then insulin gene expression is reduced." (PMID 36109786, 2022). "Our data suggest that in type 1-like diabetes with severe hyperglycemia, SGLT2 inhibition partly protected human islets by increasing the proliferation of both alpha and beta cells and improving the insulin secretory capacity." (PMID 35203411, 2022). "It turned out that preoperative hyperglycemia, regardless of whether the patients received preoperative insulin medication, was associated with an elevated risk of perioperative ischemic stroke (OR: 1.55; 95% CI: 1.01–2.4; p = 0.047; OR: 2.25; 95% CI: 1.26–3.99; p = 0.006; respectively)." (PMID 36337712, 2022). "Insulin is always used when hyperglycemia cannot be adequately controlled by oral antidiabetic drugs, and approximately half of T2DM patients receive insulin therapy for ideal glucose control." (PMID 36033393, 2022). "After transplantation, insulin therapy was stopped with a good glycaemic control during the following years.After SARS-CoV-2 infection, she developed severe hyperglycaemia requiring insulin therapy again." (PMID 36307982, 2022). "In parallel, the CREB/CRTC2 axis modulates insulin sensitivity in the liver and peripheral organs, and dysregulation of the CREB/CRTC2 axis is a major contributor to the hyperglycemia in T2D." (PMID 36232770, 2022). "Insulin also stimulates mitochondrial protein synthesis, and IGF-1 prevents hyperglycemia-induced oxidative stress, and the insulin/IGF-1 signaling defects make neurons more vulnerable to reactive oxygen species." (PMID 36361741, 2022). "The levels of fasting blood glucose and insulin were elevated in HFD-fed mice, suggesting hyperglycemia model was established." (PMID 36570152, 2022). "In addition, a study showed that when the activity of the phosphoinositide 3-kinase (PI3K)/AKT/FoxO1/PDX-1 signaling pathway in islets was upregulated, PDX-1 was redistributed from the cytoplasm to the nucleus, and insulin secretion could be improved, thus ameliorating hyperglycemia." (PMID 36551213, 2022). "High dose of STZ causes extensive injury of β cells, limiting the secretion of insulin in T1DM mice, and these mice also experience polyphagia and hyperglycemia." (PMID 36016679, 2022). "Animal experiments showed that GGQL can effectively reduce the levels of insulin, HOMA-IR, TNF-α, and IL-17 and improve the state of hyperglycemia." (PMID 36284987, 2022).
Hyperglycemia (continued). "We observed the development of hyperglycemia in rats after they had consumed the HSD for 28 days compared with animals fed the standard diet, suggesting reduced insulin sensitivity induced by the HSD in rats." (PMID 36297523, 2022). "PF-4708671 largely prevented the detrimental effects of chronic hyperglycaemia on GSIS and, partially, on insulin content." (PMID 36376280, 2022). "Procyanidins oligomers of catechin and epicatechin, as well as the monomers, were shown to suppress acute hyperglycemia by activating AMPK and insulin signaling pathways, and reduce postprandial blood glucose levels by glucose transporter 4 translocation." (PMID 36615320, 2022). "In, Colmegna and colleagues proposes a control strategy based on hyperglycaemia detection to switch between two controllers of varying aggressiveness, both designed using an LPV model of the glucose-insulin dynamics and the H∞ framework." (PMID 35528003, 2022). "The rate of insulin transport across the BBB is influenced by physiological factors such as exposure to hypercaloric diets, hyperglycemia, or a diabetic state." (PMID 35406040, 2022). "Thus, in situations characterized by hyperglycemia of the mother, such as in case of pre-existing type 1 diabetes or gestational diabetes, the increased glucose induces hypertrophy of the fetal pancreatic beta cells and increased insulin production, leading thus to fetal macrosomia." (PMID 36440208, 2022). "Heparin reduces the binding of insulin to its receptor by interacting with insulin and inhibits insulin-mediated activation of the PI3K/Akt pathway in skeletal muscle, resulting in impaired glucose uptake and hyperglycemia." (PMID 36297616, 2022). "Furthermore, voluminous and infiltrating brain tumors bring about peritumoral edema with increased intracranial pressure, a condition that is typically remedied with high-dose glucocorticoids, a drug class which may raise lactate through insulin resistance with hyperglycemia." (PMID 35862410, 2022). "Nonetheless, the best insulin regimen for hospitalized patients is still not consensual and there is recent evidence showing superiority of other regimens, namely only basal/basal-plus insulin, in terms of hyperglycemia control and without causing an increase in hypoglycemia." (PMID 35315989, 2022). "DAPA is an insulin-independent antidiabetic drug that acts as a SGLT2 inhibitor and aims to control hyperglycaemia via providing glucose excretion from the kidney through a mechanism different to that of other antidiabetic drug groups." (PMID 36326417, 2022). "Stress hyperglycemia can persist during an intensive care unit (ICU) stay and result in prolonged requirement for insulin (PRI)." (PMID 35578303, 2022). "Our study demonstrated that preoperative hyperglycemia elevated the known increased risk of perioperative stroke in type 2 diabetic patients undergoing non-cardiovascular surgeries, regardless of age, sex, history of stroke, preoperative insulin medication or surgery length." (PMID 36337712, 2022). "Notably, GLUT4 is key in the regulation of glucose homeostasis and insulin action, and decreased GLUT4 expression leads to decreases insulin-mediated glucose uptake, which could be due to exacerbated hyperglycemia, evidenced by increased glucose intolerance according to the IPGTT." (PMID 33401717, 2021). "GLUT 2 transporters are involved in glucose stimulated insulin secretion from the pancreas, but fetal pancreatic β cells do not express GLUT 2 until 7 months, impacting on the β cell's response to hyperglycaemia." (PMID 34368024, 2021). "At this point postprandial hyperglycemia is the major contributor to patients’ elevated HbA1c, since Fasting Blood Glucose (FBG) is usually well controlled by the basal insulin." (PMID 34063071, 2021).